CRP (C-reactive protein)
Diseases named in the same sentence as CRP in open-access papers (continued):
Sharing a sentence is not in itself a finding about the gene and the disease.
COVID-19 (continued). "Notably, elevated IL-6 and serum C-reactive protein (CRP) (triggered by IL-6) are markers for clinical deterioration and ventilatory support in COVID-19." (PMID 33437924, 2021). "However, for patients with influenza, symptoms of fever, cough, sputum production, and inflammatory indices of CRP, PCT, D-dimer, ESR, and fibrinogen content were higher, to a great extent, than the mild and moderate groups of COVID-19 (p < 0.05)." (PMID 34859002, 2021). "Nevertheless, the levels of inflammatory indicators, including IL-6, C-reactive protein (CRP), and lactate dehydrogenase (LDH) in patients’ plasma, were consistently higher in critical and fatal cases when compared to mild COVID-19 cases throughout the acute phase of infection." (PMID 34367117, 2021). "The decrease in CRP and D-dimer may suggest a protective effect related to ACEi/ARB use in COVID-19; however, more studies with larger sample sizes are needed to establish this effect." (PMID 33728141, 2021). "We found that the serum levels of multiple pro-inflammatory cytokines or biomarkers, including IL-6, IL-10, IL-8, TNF-α, IL-1β, IL-2R, ferritin, hs-CRP and procalcitonin were substantially elevated in non-survivors with COVID-19." (PMID 34521370, 2021). "Additionally, high-dose vitamin C remarkably reduced serum hs-CRP and PCT levels in COVID-19 patients." (PMID 33638944, 2021). "Moreover, increased ALT, AST, CRP, and LDH in severe COVID-19 patients than patients with mild disease were demonstrated in another study." (PMID 34691316, 2021). "For example, higher levels of C-reactive protein and interleukin-6 were observed in COVID-19 patients with AF, compared to patients without AF." (PMID 34199857, 2021). "One study reported an association of post-COVID depression with inflammatory biomarkers, where higher CRP was observed in COVID-19 (+) depressed patients than in COVID-19 (+) patients without depression." (PMID 34575258, 2021). "It has been previously observed that most of the COVID-19 patients have very low PCT level, while in admissions to the hospital, markers of inflammation like C-creative proteins (CRP) and biochemical and other biomarkers for the bacterial infections, however, indicated infection in the lungs." (PMID 34336223, 2021). "Levels of IL-6, mediator of the acute inflammatory response, and C-reactive protein (CRP), non-specific marker of inflammation, in these patients continue to increase over time and is significantly associated with ARDS and death in COVID-19 patients." (PMID 34595175, 2021). "The non-specific inflammatory biomarkers CRP and ferritin are used to determine the inflammatory status of COVID-19 patients." (PMID 33434221, 2021). "The described therapy option is not tailored specifically to treat COVID-19, but can be used in every condition that is marked by a sharp increase in CRP levels and in which CRP contributes to accelerated tissue destruction." (PMID 34408751, 2021). "In conclusion, CRP and FDP serum levels are positively related to the severity of COVID-19." (PMID 33526982, 2021). "The GRECCO-19 randomized study showed that treatment of patients with COVID-19 with colchicine helped reduce the time needed for normalization of the clinical condition, although no significant decrease in CRP levels was found." (PMID 34603758, 2021). "Although the clinical triage value of CRP is important, this study did not demonstrate a triage value of CRP in subjects with suspected COVID-19." (PMID 35011944, 2021). "We further found that patients with colorectal cancer and COVID-19 were more likely to have lymphopenia and higher respiratory rates and hypersensitive C-reactive protein levels than were patients with COVID-19 but without cancer." (PMID 33479506, 2021). "Some laboratory data also revealed that C-reactive protein (CRP) and IL-6 in serum may be the factors that affect the severity of COVID-19." (PMID 34681278, 2021).
COVID-19 (continued). "In a retrospective of 657 COVID-19 patients of which 46.1% had inflammatory-liver injury, there were increased neutrophils and white blood cells, decreased lymphocytes, elevated inflammatory markers such as TNF-α, hs-CRP, ferritin, IL-2R and procalcitonin." (PMID 34287285, 2021). "Additionally, COVID-19 patients have increased acute-phase proteins in serums, including procalcitonin (PCT), serum amyloid A (SAA), C-reactive protein (CRP), and serum ferritin (SF)." (PMID 33757410, 2021). "Compared to those with non-severe COVID-19, patients with severe COVID-19 had significantly higher circulating levels of neutrophil-to-lymphocyte ratio, C-reactive protein, procalcitonin, D-dimer, IL-6 and IL-10 both in MAFLD and in non-MAFLD patients." (PMID 33763027, 2021). "We found that for IL-6 and CRP showed a similar pattern as H3.1 nucleosomes in which there was a statistically significant difference in COVID-19 patients in ICU compared to the in outpatient/ER but not in the regular hospital ward." (PMID 33816549, 2021). "Inaddition, many patients in the trauma settings have high levels of inflammatoryblood markers, such as ESR (erythrocyte sedimentation rate), CRP (c-reactiveprotein), LDH (lactate dehydrogenase), and procalcitonin, that make these markersless helpful in the diagnosis of COVID-19 specifically." (PMID 38603021, 2021). "In this study, we longitudinally analyzed MDW values in a cohort of 87 COVID-19 patients consecutively admitted to our hospital, showing significant correlations between MDW and common inflammatory markers, namely CRP (p < 0.001), fibrinogen (p < 0.001) and ferritin (p < 0.01)." (PMID 34135448, 2021). "At the various blood tests following COVID-19 diagnosis, there were no significant variations over time for hemoglobin, white blood cells, platelet count, CRP, LDH, or ALT." (PMID 34684237, 2021). "As the importance of JAK/STAT in the pathogenesis of COVID-19 was shown previously, baricitinib is a JAK inhibitor that leads to the inactivation of STATs and a decrease in the serum levels of IgG, IgA, IgM, and CRP." (PMID 34068970, 2021). "As evaluated during the acute phase of COVID-19, patients with moderate forms of severity prevailed (76.47%, p < 0.001); based on the CCT, they had a more severe pulmonary injury and higher degrees of inflammation, with more increased CRP (p < 0.001)." (PMID 34830554, 2021). "A few studies have demonstrated that a higher CRP expression on admission was observed in severe COVID-19 patients compared with non-severe COVID-19 patients." (PMID 34372767, 2021). "Combining the correlation analysis with the reference value analysis, we found that the critical COVID-19 patients are usually accompanied by low values of lymph, eGFR, albumin and Serum Sodium, high values of LDH, hs-CRP, indirect bilirubin, creatinine and INR." (PMID 33557818, 2021). "Given its unknown biological specifics in the critical care context, we have analyzed the longitudinal course of IL-6, together with C-reactive protein (CRP), procalcitonin (PCT) and leucocyte counts in 16 COVID-19 patients." (PMID 34315504, 2021). "Early in the COVID-19 pandemic, it was established that a raised CRP, which is widely used as a biomarker of bacterial infection in the UK, reflected severity of illness rather than bacterial superinfection in COVID-19 patients." (PMID 34062898, 2021). "First reports suggest that administration of MSCs is safe in patients with ARDS and may limit the cytokine storm (by reducing the levels of C-Reactive Protein, IL-6 or TNF-α) and improve oxygenation in severe COVID-19 patients." (PMID 34887773, 2021). "It has been reported that the levels of CRP were significantly increased in severe cases compared to non-severe COVID-19 patients." (PMID 34222268, 2021). "In this regard, the increase of blood inflammatory markers (e.g., CRP, IL-6, TNF-α, IL-1, etc.)in GBS tested cases may reinforce the hypothesis of a systemic inflammatory storm in COVID-19." (PMID 32840686, 2021).
COVID-19 (continued). "C-reactive protein levels, which are increased in COVID-19 patients with pneumonia, were not elevated in the infected macaques." (PMID 34452537, 2021). "For example, COVID-19 patients often have no rise in CRP, PCT, and WBC, which was in accordance with the results of other studies." (PMID 33996842, 2021). "This study reports that COVID-19 patients with GI symptoms had significantly lower D-dimer levels than those without such symptoms, while serum ferritin, lactate dehydrogenase, and C-reactive protein levels were not significantly different." (PMID 34290914, 2021). "In multivariate logistic regression analysis to detect the factors predicting mortality among older patients with COVID-19, malignancy; dyspnea; NLR; the highest values of CRP, creatinine, and LDH; azithromycin use; and SpO2 values on admission were independently associated with mortality." (PMID 33315348, 2021). "COVID-19, Diabetes Mellitus, SARS-CoV2, inflammation, CRP, Glucose." (PMID 33842709, 2021). "In contrast, in patients with COVID-19 pneumonia, procalcitonin and C-reactive protein were negative predictors for COVID-19 pneumonia, whereas progranulin and interleukin-6 were positive predictors of COVID-19." (PMID 34476621, 2021). "Also, the higher NLR, CRP, ESR, LDH as well as SC concentrations in COVID-19 patients reflect the systemic immune-inflammation as a part of SARS-CoV-2 infection." (PMID 34753964, 2021). "For the ordinal and the binary lung damage variables, we found a correlation for the whole sample (RT-PCR COVID-19 positive and negative), which was significant for lymphocytopenia, CRP, LDH, d-dimer, and fibrinogen." (PMID 33832103, 2021). "We also observed higher neutrophil counts and C-reactive protein levels in non-survivor vs survivor cancer patients infected with COVID-19." (PMID 34094950, 2021). "Blood tests to measure neutrophil/lymphocyte ratio (NLR) and levels of ferritin, CRP, D-dimer, complement components (C3 and C4), cytokines, and lymphocyte subsets, as well as SARS-Cov-2 RT-PCR tests, were performed in COVID-19-confirmed cases within 48 hours of admission." (PMID 34422145, 2021). "In addition, C-reactive protein (CRP), an acute-phase protein produced in the liver, is a vital marker for people with COVID-19 because its rapid increase is observed in most severe cases." (PMID 33808640, 2021). "Additionally, COVID-19 patients had significantly higher levels of D-dimer, aPTT, fibrinogen, CRP, ferritin and LDH, and in the severe group of patients, these parameters were higher than in mild COVID-19 patients." (PMID 33692788, 2021). "In severe cases of COVID-19, excessive inflammation in the lung alveoli leads to severe hypoxia and ARDS and has features of systemic cytokine release syndrome presenting with high fever and abnormal CRP." (PMID 35095877, 2021). "Indeed, calprotectin was better than CRP and PCT for admitting COVID-19 patients to the ICU, with an AUC at 0.80 (vs. 0.66 and 0.60, respectively)." (PMID 34299080, 2021). "However, in the COVID-19 cohort, RDW, D-dimer, CRP, and procalcitonin were similarly abnormal compared to before treatment, showing a slow recovery in those values due to COVID-19 infection despite such ICU patients having been discharged from critical care." (PMID 34485324, 2021). "• IL-6 levels follow the response to novel COVID-19 therapies, however do not offer a clinical advantage over C-reactive protein and bedside observations in predicting severe disease." (PMID 33815405, 2021). "Overall, there is a significant (p < 0.05) increase in CRP level [25.35 (5.22–66)] in total COVID-19 positive patients as compared to the non-COVID-19 group." (PMID 33861750, 2021). "We found significant direct correlations between galectin-3, CCL2, PON1, IL-6, IL-10, CRP, ACE2, and angiotensin II concentrations in COVID-19 positive patients as well as with aminotransferase activities and triglycerides, and inverse correlations with HDL-cholesterol." (PMID 34205807, 2021).
COVID-19 (continued). "In a recent systemic review, it was found that CRP levels are significantly higher in severe COVID-19 patients than in non-severe patients." (PMID 35011944, 2021). "Several reports have also observed higher concentrations of C-reactive protein, IL-6, IL-10, ferritin, leukocytes and lower lymphocyte percentage in severe COVID-19 patients compared to that of non-severe patients." (PMID 33995267, 2021). "Among routine markers of inflammation, PCT and TNF-α, but not CRP, IL-6 or ferritin, were higher in COVID-19 patients on MV compared to those not on MV." (PMID 33058027, 2021). "Fifth, CRP is not distinct for diagnosis of COVID-19; nevertheless, it is an established biochemical parameter for assessment of severity in infectious and inflammatory diseases." (PMID 33919094, 2021). "Significant reduction in lymphocyte count, and marked increase in C-reactive protein (CRP), alanine amino-transferase (ALT), aspartate aminotransferase (AST), direct bilirubin (DBIL), and glucose were exhibited in severe COVID-19 patients, which were consistent with previous findings." (PMID 33712622, 2021). "We investigated PCT and CRP kinetics in critically ill COVID-19 patients treated with dexamethasone with or without tocilizumab, and assessed the value of these biomarkers to detect secondary bacterial infections." (PMID 34353339, 2021). "The most common laboratory abnormalities among hospitalized patients with COVID-19 include lymphopenia, elevated aminotransaminase, lactate dehydrogenase (LDH), and inflammatory markers such as C-reactive protein (CRP), ferritin, and the erythrocyte sedimentation rate (ESR)." (PMID 34208017, 2021). "Thus, routine testing for NLR, CRP, ESR, Troponin-I, BUN, creatinine, AST, ALT, CK-MB, LDH and D-dimer in severe COVID-19 is beneficial in monitoring clinical progression and can predict outcome of the disease." (PMID 34760713, 2021). "As for systemic organ indices, our results revealed that the severe COVID-19 group presented relatively elevated WBC counts, neutrophil percentages, and neutrophil counts; high CRP levels; and decreased lymphocyte percentages, lymphocyte counts, and platelet counts." (PMID 33456349, 2021). "Our results demonstrate that increasing the levels of IL-6 correlate to disease severity and identifying particularly well those patients who evolved to more severe stages of COVID-19, a pattern not observed with other markers such as CRP." (PMID 33679753, 2021). "Higher blood levels of inflammatory biomarkers (e.g. CRP) and cytokines (e.g. IL2, IL7, IL10, etc.)have been reported in COVID-19 patients admitted to the ICU3, and IL6 and IL10 have been determined to be strong discriminators for severe disease and death, consistent with our findings." (PMID 33627696, 2021). "Then, the cytokines (including CRP, Ferritin, IL-6, TNF-α, GM-CSF, IP-10, and MCP1α/1β) in the serum of severe patients with COVID-19 were higher than that in the mild patients with COVID-19, while the number of T and NK cells decreased and the number of neutrophils increased." (PMID 34667157, 2021). "In severe COVID-19 cases, the serum concentrations of CRP are increased in non-survivors compared to non-severe COVID-19 patients and survivors." (PMID 35011944, 2021). "Our results show that the use of convalescent plasma as a therapy to non-critical COVID-19 patients significantly improved their inflammatory status, especially the D-dimer, CRP and ferritin markers." (PMID 34822419, 2021). "Similarly to some previous studies, we observed increased peripheral blood levels of immune-inflammatory parameters such as AST, LDH, CRP, IL6, and PT in COVID-19 patients compared to controls." (PMID 34945761, 2021). "The mean peak WBC count; mean peak neutrophil count; and mean peak CRP, LDH, and ferritin levels in our patients are noted to meet the criteria mentioned in this paper indicating that pneumothorax in patients with COVID-19 tends to occur in those with more severe disease." (PMID 34466329, 2021).
COVID-19 (continued). "Inflammatory markers, namely, C-reactive protein (CRP), Interleukin 6 (IL-6), and erythrocyte sedimentation rate (ESR) (MMD= 36.97 mg/l, 17.37 pg/ml, 21.93 mm/hr, respectively) were raised in severe COVID-19 cases." (PMID 34760713, 2021). "COVID-19 positive individuals with diabetes have been shown to have significantly increased levels of IL-6 and C-reactive protein compared to COVID-19 patients without diabetes." (PMID 34444990, 2021). "Previous researches demonstrated that evidently decreased lymphocytes, increased platelets, CRP, LDH and D-dimer in COVID-19 patients might indicate that inflammation was severe and disease might deteriorate." (PMID 33588779, 2021). "Proinflammatory molecules, such as IL-2, IL-4, IL-5, IL-6, IL-10, IL-13, TNF-α, IFN-Υ, and CRP, were found at higher levels in COVID-19 patients with DM than in COVID-19 patients without DM." (PMID 34786431, 2021). "Lymphocytopenia, C-reactive protein (CRP), lactate dehydrogenase (LDH), d-dimer, and fibrinogen increased levels occurred in most patients without statistically significant differences between the 2 groups with CT scans suggestive for COVID-19." (PMID 33832103, 2021). "Consistently, our study demonstrated an elevated CRP level in COVID-19 patients with PE compared to that in those without." (PMID 34362946, 2021). "C-reactive protein (CRP) and procalcitonin (PCT) are commonly used to differentiate between bacterial infections with other inflammatory conditions, but it is unclear how this can be applied to COVID-19 to guide antimicrobial management." (PMID 34496795, 2021). "Plasma biomarkers in PIMS-TS and COVID-19 children showed a positive correlation with CRP and a negative correlation with the lymphocyte count and sodium levels." (PMID 33813138, 2021). "The severity of COVID-19 is represented by an excessive production of IL-6, TNF-α, and CRP." (PMID 34867458, 2021). "PCT can be used as a marker for bacterial infection and may be more effective than other commonly used clinical indicators such as CRP, ESR, and WBC.21, –23 Our research showed higher PCT had relationship with the severity of COVID-19." (PMID 33663273, 2021). "In this study, we found that the difference of WBC and neutrophil counts and CRP is not significant in severe cases with COVID-19." (PMID 34423043, 2021). "In their study, these biomarkers were significantly different in COVID-19-positive compared to -negative patients, but only lactate dehydrogenase and C-reactive protein values were outside of the normal ranges." (PMID 33946171, 2021). "High serum levels of CRP, AST, LDH, and ferritin in patients with COVID-19 may indicate that liver dysfunctions have been involved, and target treatments should be taken in time to prevent irreversible organ damage and increased risk of mortality." (PMID 34185801, 2021). "Nonetheless, it is plausible that immune dysregulation is responsible for increased COVID-19 severity in patients with diabetes, since we observed higher NLR and elevated levels of serum CRP, ESR, and LDH in diabetic patients infected with SARS-CoV-2 in the present study." (PMID 33746672, 2021). "Clinically, patients with colorectal cancer and COVID-19 were more likely to have lymphopenia, higher respiratory rate, and high hypersensitive C-reactive protein levels than matched patients with COVID-19 but without cancer." (PMID 33479506, 2021). "Significantly elevated CRP, lactic dehydrogenase (LDH), and serum ferritin could signal or predict deterioration of COVID-19 and related complications." (PMID 33224906, 2020). "The percent of detecting COVID-19 positive RT-PCR (98%) for suspected individuals using ROC showed best cutoff of ≤21.8 for lymphocytes %, ≥67.7 for neutrophils, ≥37.5 for ESR, ≥6.2 for CRP and ≥7.15 for WBCs." (PMID 33738019, 2020).